MDK (midkine)
Diseases named in the same sentence as MDK in open-access papers (continued):
Sharing a sentence is not in itself a finding about the gene and the disease.
glioma (continued). "MDK resulted in 1 of the top possible mediators of the interaction between glioma cells and oligodendrocytes through its ligand LRP2." (PMID 33155039, 2020). "THC resistance can occur in glioma cells, and growth factor midkine (Mdk) has been shown to be involved in this resistance." (PMID 32708138, 2020). "Of these, ten genes (CTSZ, EFEMP2, ITGA5, KDELR2, MDK, MICALL2, MAP 2 K3, PLAUR, SERPINE1 and SOCS3) can potentially classify patients with gliomas into different risk groups." (PMID 32878880, 2020). "Here the authors show that midkine-dependent activation of a neuron-T cell-microglia axis promotes the growth of optic pathway gliomas." (PMID 32358581, 2020). "We had previously found that the neurotrophic factor MIDKINE (MDK) promotes resistance to glioma cell death." (PMID 32308772, 2020). "We also observed that MDK promoter methylation was significantly decreased but mRNA expression was increased in high-grade tumors compared to low-grade gliomas." (PMID 31811117, 2019). "A few recent studies indicated that elevated midkine expression, assayed with immunohistochemistry or with the mRNA amounts, was a poor prognostic marker in lung carcinoma and glioma." (PMID 28335760, 2017). "ACSL5 is highly expressed in glioma and drives the cell growth through midkine (MDK) in the acidic microenvironment." (PMID 27171439, 2016). "Acyl-CoA synthetase 5 (ACSL5) promotes glioma cell survival under low pHe conditions through midkine (MDK) signaling." (PMID 24198789, 2013). "Therefore, we evaluated MDK expression in healthy brain tissues and gliomas in our combined dataset." (PMID 40835683, 2025). "This study found an elevated expression level of MDK in human glioma tissues." (PMID 40468625, 2025). "This link has aroused our interest in the role of MDK in the treatment of glioma by TMZ." (PMID 40468625, 2025). "The findings of this study may aid investigations on therapies targeting MDK and related biomarkers in glioma, the development of ACT001 as a glioma treatment, and the expansion of reference treatment protocols for glioma." (PMID 40468625, 2025). "Hence, the impact of altered MDK levels on the protein expression profile in human glioma cells was investigated using proteomic analysis, leading to the identification of affected signalling pathways." (PMID 40468625, 2025). "Focusing on the MDK/c‐Myc complex could be an effective approach to combat resistance to TMZ in glioma." (PMID 40468625, 2025). "Previous studies have shown that MDK is highly expressed in glioma cells." (PMID 40468625, 2025). "To clarify the relationship between MDK and c‐Myc and the regulation of their protein complex on the biological behaviours of glioma, we examined the expression of the MDK and c‐Myc genes in glioma tissues and adjacent tissues." (PMID 40468625, 2025). "Compared with normal brain tissue, both c-Fos and MDK were highly expressed in glioma." (PMID 40527884, 2025). "Therefore, MDK not only functions as an important biomarker but also serves as a crucial target in glioma therapy." (PMID 40468625, 2025). "Therefore, ACT001 targets the MDK/c‐Myc complex to inhibit the malignant progression of glioma and increases its sensitivity when combined with TMZ." (PMID 40468625, 2025). "The results showed that c-Fos and MDK were correlated in both gliomas and GBMs." (PMID 40527884, 2025). "Therefore, a regulatory relationship can be found between MDK and c‐Myc in glioma cells, and changes in MDK expression can affect the expression and function of c‐Myc." (PMID 40468625, 2025). "Studies of low-grade gliomas (LGGs) using neurofibromatosis type 1 (NF1) as a genetic model system describe MDK as an upstream mediator regulating the activation of T cells, the release of cytokines, and thereby tumor growth in NF1-mutant murine and human neurons." (PMID 38098484, 2023). "However, it has been shown that in gliomas midkine (MDK) can bind to LRP1 on tumor-infiltrating CD8+ T cells leading to increased CCL4 expression on T cells." (PMID 37020553, 2023).
glioma (continued). "MDK downregulation suppressed glioma cell proliferation and the tumour growth in nude mice." (PMID 32592428, 2020). "Previously, MDK has been reported as a secretion protein that promotes glioma cell proliferation." (PMID 32120790, 2020). "Moreover, we demonstrate that NF1-mutant neurons support glioma growth by producing MDK, which activates T cells to produce Ccl4, a cytokine that induces microglia to express a critical glioma growth factor (Ccl5)." (PMID 32358581, 2020). "Nevertheless, it cannot be discarded that some of these receptors may also contribute - at least to some extent - to MDK actions in gliomas or GICs." (PMID 32308772, 2020). "Furthermore, ALK is a receptor for midkine, through which midkine contributes to glioma progression and thus renders glioma cells resistant to autophagy-mediated cell death and antitumoral effects of cannabinoids." (PMID 28430645, 2017). "In addition, we discovered that reducing MDK expression increases responsiveness to chemotherapy, indicating that MDK could serve as a biomarker and treatment target for gliomas." (PMID 40468625, 2025). "Furthermore, after MDK was knocked down, the invasion of glioma cells in vitro was suppressed." (PMID 40468625, 2025). "Consequently, focusing on MDK has emerged as a novel strategy for treating glioma." (PMID 40468625, 2025). "Notably, the mean MDK isoform proportions were similar to gliomas in the combined dataset." (PMID 40835683, 2025). "Moreover, MDK was found to be a potential biomarker for glioma, and targeting MDK may be beneficial for glioma treatment." (PMID 40468625, 2025). "Finally, we analyzed whether there was a correlation between transcription factor c-Fos and MDK in gliomas using TCGA and CGGA databases." (PMID 40527884, 2025). "HBS-101, a novel midkine inhibitor, reduced optic nerve proliferation, normalized RNFL thickness, and decreased the expression of tumor (Neu4, Gpr17) and TME (Ccl2, Ccl3, Ccl4, Ccl5) genes, supporting its continued development as a targeted therapy for pediatric NF1-associated glioma." (PMID 41497446, 2025). "MDK protein levels present in the medium as well as MDK mRNA levels were dramatically increased in GICs-enriched cultures (hereafter named GICs cultures) as compared with the levels of this neurotrophic factor in the corresponding cultures of serum-differentiated glioma cells." (PMID 32308772, 2020). "The oncogenic role of MDK, promoting proliferation and pharmacological resistance in glioma, may involve the release of Sonic Hedgehog (SHH) from LRP2 sequestration in oligodendrocytes, thus functioning to activate one of the best-known activators of proliferation and stemness of brain tumors." (PMID 33155039, 2020). "Additionally, MDK, which is upregulated by Wnt/β-catenin in gliomas, contributes to tumor progression and metastasis by enhancing the growth, survival, and EMT of cancer cells; this is because MDK activates a Notch signaling that cross-talks with PI3K/AKT and STAT3 signaling." (PMID 32120790, 2020). "The existing selective pressure for higher MDK expression, favoring its specific isoform (ENST00000395566), suggests its tumor-promoting role in gliomas." (PMID 40835683, 2025). "Thus, expression of MDK mRNA could forecast the outcome for individuals with glioma, where a high expression level is linked to a negative prognosis." (PMID 40468625, 2025). "In this manner, Nf1-mutant neurons initiate a paracrine stromal cascade in which midkine induces CD8+ T cells to produce Ccl4, which in turn stimulates TAM expression of Ccl5, a cytokine that increases glioma growth." (PMID 41497446, 2025).
glioma (continued). "At first, our analysis revealed a consistent picture of high MDK expression in grade II, III, and IV gliomas compared to healthy brain tissues, with its expression increasing proportionally to the tumor grade." (PMID 40835683, 2025). "Similar to the altered expression of MDK during inflammation and cancer, expression of SP1 is also elevated in human glioma tissues more than in normal tissue." (PMID 37240085, 2023). "Overexpression of midkine (MDK), a key transcriptional factor in DDR pathways can remodel the glioma immunosuppressive microenvironment by promoting M2 polarization of microglia." (PMID 37086071, 2023). "Midkine (MDK), an anaplastic lymphoma kinase (ALK) ligand, also promotes the resistance of glioma cells to anticancer therapies such as radiotherapy (RT) and temozolomide (TMZ)." (PMID 35625997, 2022). "Signaling through the hepatocyte growth factor receptor (c-MET) and the midkine (ALK ligand) promotes gliomagenesis and glioma stem cell maintenance, contributing to the resistance of glioma cells to anticancer therapies." (PMID 35625997, 2022). "For example, Sp1 positively regulates MTA2 and midkine (MDK) expressions in gastric cancer tissues 30 and glioma cells 29, respectively." (PMID 26763486, 2016). "Glioma cells develop resistance to cannabinoid treatment due to the upregulation of Amphiregulin (EGFR family ligand) and the growth factor midkine (Mdk)." (PMID 25115386, 2014). "This pathological hyperactivity prompts midkine (MDK) —a heparin‐binding growth factor—to stimulate T lymphocyte CCL4 secretion, triggering subsequent microglial CCL5 release; a pivotal mitogenic stimulus for glioma proliferation." (PMID 41583906, 2026). "Notably, crizotinib can suppress the MDK/ALK axis and effectively enhance the response of glioma-initiating cells (GIC) to TMZ in vitro and using GIC-derived xenograft models." (PMID 38334610, 2024). "In the CNS, MDK-dependent ALK signal transmission in glioma cells results in the activation of the Akt/mTOR1 axis, preventing autophagy-mediated cell death by tetrahydrocannabinol (THC), thereby contributing to the cannabinoid-resistance of gliomas." (PMID 38098484, 2023). "GBM cells from all four clusters expressed up to 10 different MDK/PTN receptor genes, suggesting that these GBM cells can respond to MDK and PTN cytokines produced by the glioma microenvironment and/or produced auto-/ paracrine by GBM cells, as demonstrated for GBM-34, -49, -109, and -228." (PMID 34502484, 2021). "Specifically, our group and others previously demonstrated that enhanced MDK levels correlated with worse prognosis in GBM patients 13, 19, thereby suggesting that this growth factor may play a role in glioma generation and progression." (PMID 32308772, 2020).
lung carcinoma (25 papers, 2013 to 2025). "In lung cancer, previous studies have shown a strong association between elevated MDK expression (at both mRNA and protein levels) and malignant status, as well as poor prognosis in NSCLC patients." (PMID 40520001, 2025). "Exogenous MDK and MDK from cancer-associated fibroblasts was able to decrease cisplatin-induced cell death in oral squamous cell carcinoma, ovarian cancer, and lung cancer by upregulating the expression of BCL2." (PMID 40429950, 2025). "MDK is part of the diagnostic biomarker blood test that can detect early-stage lung cancer in at-risk populations." (PMID 37240085, 2023). "Moreover, a specific type of lipid-associated macrophage population, Ribonuclease A Family Member 1 (RNASE1-M), which is regulated by Midkine‌ (MDK), has been identified as being associated with osimertinib resistance and lung cancer development." (PMID 41425254, 2025). "Midkine, a heparin-binding multifunctional growth-promoting protein is overexpressed in various solid tumours and high expression has been shown to be associated with poor survival in breast and lung cancer." (PMID 27689402, 2016). "Thus, midkine may be a good indicator for identifying high-risk patients and a therapeutic target for lung cancer." (PMID 27974680, 2016). "Bioinformatics analysis revealed that Midkine (MDK), a heparin-binding growth factor known to promote migration, is highly elevated in breast and lung cancer patients and is related with osteoclast formation." (PMID 40520001, 2025). "In our current study, we conducted a cross-analysis of the GEO database for lung cancer, breast cancer, and osteoclast formation, identifying MDK as the most likely regulator of lung and breast cancer bone metastasis." (PMID 40520001, 2025). "We utilized publicly available databases (miRDB, TargetScan, and microT-CDS) and our previously reported Ugonin P-treated lung cancer miRNA sequencing data 30 to identify potential miRNAs targeting MDK." (PMID 40520001, 2025). "MDK and SPINT2 were selected due to the observed differences in overall survival while GDF15 levels have been associated with different stages of lung cancer in patients." (PMID 38260835, 2023). "As a soluble secreted protein, MDK is abnormally expressed at high levels in various human malignancies including lung cancer." (PMID 36721112, 2023). "In lung cancer, midkine (MDK) enhances the EMT capability of the cancer cells by TGF-β, Wnt, and Notch2 signaling pathways." (PMID 34722623, 2021). "In the present study, we detected MDK expression in lung cancer tissues and cells, suggesting that MDK expression was increased in lung cancer, and overexpression of MDK promoted lung cancer stem cell activity." (PMID 32592428, 2020). "In this study, we explored the functions of miR‐188 in the biological characteristics of lung cancer stem cells with the involvement of MDK and the Hippo pathway." (PMID 32592428, 2020). "Overexpression of MDK has been revealed in a variety of cancers, including gastric cancer, breast cancer and lung cancer." (PMID 32592428, 2020). "We found that the mRNA and protein expressions of MDK were notably increased after miR‐188 overexpression, indicating that MDK is a downstream transcript of miR‐188 and fulfils key functions in lung cancer progression." (PMID 32592428, 2020). "Collectively, the present study demonstrated that miR‐188 played a suppressive role in the biological characteristics of lung cancer stem cells via targeting the MDK‐mediated Hippo pathway." (PMID 32592428, 2020). "The MDK-Notch2-NF-κB-Hes-1 signal axis increased the expression of mesenchymal markers, and lung cancer cells became more disorganized and moveable." (PMID 32847073, 2020). "In summary, our study highlights a new molecular mechanism involving miR‐188, MDK and the Hippo signalling pathway, which plays a suppressive role in biological activity of lung cancer stem cells." (PMID 32592428, 2020).
lung carcinoma (continued). "Secreted MDK elevated angiogenesis by increasing the interactions of endothelial cells and lung cancer cells via paracrine signaling." (PMID 32847073, 2020). "We also identified MDK as a target of miR‐188, and overexpression of MDK was found in lung cancer samples." (PMID 32592428, 2020). "Midkine (MDK) is known as a heparin‐binding growth factor that is upregulated in some malignant tumours, including lung cancers." (PMID 32592428, 2020). "Overexpression of MDK were observed in many cancers, including lung cancer, ovarian carcinoma and thyroid carcinoma." (PMID 30001734, 2018). "It has been shown that midkine overexpression is observed in a variety of human cancers such as gastrointestinal cancer, colorectal cancer, lung cancer, breast cancer, pancreatic cancer, and HCC." (PMID 27813495, 2016). "Elevated levels of MDK, a heparin-binding growth factor, have been observed in serum collected from patients with a broad range of solid tumors, including lung cancer." (PMID 26279647, 2015). "An 8-marker model was developed (TFPI, MDK, OPN, MMP2, TIMP1, CEA, CYFRA 21–1, SCC) which accurately distinguished subjects with lung cancer (n = 50) from high risk smokers (n = 50) in an independent validation study (AUC = 0.775)." (PMID 26279647, 2015). "MEOX2 was uniformly higher methylated in all lung cancer samples, while the methylation of the other three genes was correlated with either the differentiation status of the tumor (MDK, LAPTM5) or with the tumor histopathological type (FGFR3)." (PMID 23086271, 2013). "Inhibition of MDK with iMDK provides a potential therapeutic approach for the treatment of lung cancers that are driven by MDK." (PMID 23976985, 2013). "Midkine (MDK) is a heparin-binding growth factor that is highly expressed in many malignant tumors, including lung cancers." (PMID 23976985, 2013). "In vitro, iMDK inhibited the growth of lung cancer cells by inhibiting MDK protein levels." (PMID 40527884, 2025). "The expression and secretion of midkine (MDK) protein in lung cancer cells is regulated by HIF-1α." (PMID 37046617, 2023). "Moreover, the MDK targeting strategy provides a potential therapeutic target for the treatment of MDK-expressing lung cancers." (PMID 32847073, 2020). "Overexpressed MDK promoted the malignant behaviours of lung cancer stem cells." (PMID 32592428, 2020). "MDK appears to play a role in both angiogenesis and lung cancer metastasis." (PMID 26279647, 2015). "iMDK inhibited the cell growth of MDK-positive H441 lung adenocarcinoma cells that harbor an oncogenic KRAS mutation and H520 squamous cell lung cancer cells, both of which are types of untreatable lung cancer." (PMID 23976985, 2013). "Inhibition of MDK by siRNA suppresses cell growth of cancer cells that express MDK, indicating that MDK might be a potential target for lung cancer therapy." (PMID 23976985, 2013). "These in vivo results indicated that iMDK, an MDK target inhibitor, is a likely promising therapeutic anti-tumorigenic, -EMT, and -angiogenic drug target in lung cancers." (PMID 32847073, 2020). "In this study, we found that midkine (MDK) is up-regulated by hypoxia, more specifically, MDK mRNA, and the expression and secretion of the protein are regulated by HIF-1α in lung cancer cells." (PMID 32847073, 2020). "Moreover, MDK increased the EMT ability and proliferation pathway of lung cancer cells via the autocrine pathway." (PMID 32847073, 2020). "Although the serum midkine level does not depend on tumor progression, the suppression of midkine expression inhibited lung cancer cell growth in vitro and in vivo by inducing apoptosis and inhibiting the PI3K signaling pathway." (PMID 27974680, 2016). "These in vivo results indicate that iMDK is likely to be a promising therapeutic anti-tumorigenic/angiogenic drug targeting MDK-expressing lung cancer without side effects." (PMID 23976985, 2013).
lung carcinoma (continued). "The results of the present study showed that MDK, WFDC2, and CXCL14 were upregulated in early-stage LUAD and upregulated expressions of three secreted proteins promoted the proliferation of lung cancer cells, suggesting that these proteins might be involved in the tumorigenesis of LUAD." (PMID 36721112, 2023). "The implications of midkine upregulation in HEKn cells expressing HPV16 E6 and E7 remains to be explored and may be worth pursuing, as midkine has garnered attention as a therapeutic target for one type of lung cancer." (PMID 36016386, 2022). "MDK is expressed in HEK293 embryonic kidney cells, H441 lung adenocarcinoma cells and H520 lung squamous cell carcinoma cells but not in A549 lung carcinoma cells or non-transformed NHLF cells." (PMID 23976985, 2013).